CD4 (CD4 molecule)
Diseases named in the same sentence as CD4 in open-access papers (continued):
Sharing a sentence is not in itself a finding about the gene and the disease.
melanoma (continued). "FoxP3+ frequencies within the CD4+ T cell subset in fresh PBMC for this patient cohort (n = 11) were higher compared to fresh PBMC isolated from healthy controls (n = 10; C14-23) (p = 0.043), although the difference was modest as shown for other melanoma patients." (PMID 34926643, 2021). "Furthermore, in melanoma, RBM26-AS1 dysregulation has been found in CD4 memory T cells." (PMID 34746237, 2021). "Interestingly, STAT3 depletion and anti-PD-1 therapy decreased the percentages of CD8+ and CD4+T cells, leading to an increased CD8/CD4 ratio in STAT3 downregulation and PD-1 blockade combinational treatment in melanoma according to monitoring mice in the PD-1 blockade group." (PMID 33936081, 2021). "Double‐positive (DP) T‐lymphocyte (CD4+/CD8high) populations of effector/memory T‐cells [both in the peripheral blood (PBL) and within the tumour (TIL)] have been reported to expand in MeLiM animals during melanoma regression and it is postulated that they are involved in the regression process." (PMID 32652526, 2020). "It remains to be determined whether these effects also reflect clonal diversity even though CD4 (but not CD8) T cell clonal diversity prior to CTLA-4 blockade significantly improved survival in melanoma patients." (PMID 32630460, 2020). "Flow cytometry analysis performed on tumors collected 11 days after melanoma cell inoculation, a time point when tumors begin to shrink in Siah2−/− mice revealed a comparable number or proportion of CD45.2+, CD4+, CD8+, CD11b+ F4/80+, CD11c+, and CD11b+GR1+ cells in both genotypes." (PMID 31911617, 2020). "The tumour‐infiltrating lymphocytes in the second stage were identified as cytotoxic (CD4−/CD8+) and were found at much higher levels than in the peripheral blood, suggesting that the cytotoxic T‐lymphocytes play a key role in the final elimination of the melanoma." (PMID 32652526, 2020). "The results showed that the percentages and activation of CD8+ T cells and NK cells in the melanoma tissues were significantly increased after treatment with ssRNA and dual-function vectors, whereas the proportions and activation of CD4+ T cells did not change." (PMID 31849942, 2019). "B16F10 melanoma cells were cultured in the presence or absence of splenic CD4+ or CD8+ T cells from tumour-bearing mice, cryo-thermal with isotype treated mice and cryo-thermal with Siglec-F mAb treated mice at various ratios for 24 h, and the cell viability (%) was determined." (PMID 31519961, 2019). "To see whether TTRAP have a tumor-promoting effect in vivo, we subcutaneously (s.c.)inoculated B16F10 melanoma cells into C57BL/6 mice with or without co-administration of control CD4+ T cells or TTRAP." (PMID 31300052, 2019). "The tumor cells were positive for CD68, S100, CD4 and lymphocyte common antigen, while epithelial membrane antigen, HMB-45, CK AE1/AE3, myogenin, desmin, CD1a, CD21 and SALL-4 were negative thus ruling out rhabdomyosarcoma, extrarenal rhabdoid tumor, Langerhans cell sarcoma and malignant melanoma." (PMID 31890359, 2019). "While in healthy individuals the majority of TCR Vβ-gene families of CD4+ T cells showed Gaussian distributions typical of unselected T-cell populations, significantly higher numbers of TCR Vβ-gene families of CD4+ blood T cells in melanoma patients exhibited repertoire restrictions (p = 0.0056)." (PMID 31275310, 2019). "pS14-WWOX7-21 peptide failed to block melanoma cell metastasis and yet induced significant upregulation of the expansion of spleen helper CD4+ T cells (2-fold increase), cytotoxic CD8α+ T cells (25-fold increase) and CD19+ B cells (14-fold increase) in the germinal centers." (PMID 31752354, 2019). "However, FTO knockdown in melanoma cells did not affect the number of IFNγ-producing CD4+ or CD8+ TILs s." (PMID 31239444, 2019).
melanoma (continued). "Moreover, we demonstrated that co-culture of non-activated PBLs with TRAIL-R2+ melanoma cells in the presence of the scDb also led to activation of CD4+ and CD8+ T-cell proliferation, as shown by CFSE assay, but not of CD3−/CD19+ cells." (PMID 31708930, 2019). "Finally, murine YUMM melanoma tumors established in SCID mice (lacking CD4+ and CD8+ T cells) were also inhibited by systemically delivered G-1." (PMID 29336307, 2018). "Additionally, intratumoral and peripheral CD4+FOXP3−PD-1hi nonconventional Tregs in NSCLC as well as melanoma patients were reported as prognostic biomarkers for anti-PD-1 and anti-CTLA-4 therapies." (PMID 30546008, 2018). "In fact, approximately half of the PD-1+ TILs were CD4+ (Teff or Treg), which is consistent with studies of archival HNSCC, ovarian cancer, and Hodgkin lymphoma FFPE specimens studied by IHC/IF; and melanoma, renal cell carcinoma, and MCC specimens studied by flow cytometry." (PMID 30285852, 2018). "Therefore, we cannot completely rule out the participation of CD4+ T cells in the priming of protective CD8+ T cell responses against i.v. melanoma." (PMID 30319653, 2018). "Notably, CD4+ CTL able to kill specific tumor cells have been described in several cancer types, including non-small-cell lung carcinoma (NSCLC), cutaneous T-cell lymphoma, and melanoma; for review, see Ref." (PMID 29403496, 2018). "However, the administration of an anti-CD4 Ab 30 days after priming, and prior to i.v. melanoma challenge, did not affect protection." (PMID 30319653, 2018). "Thus, circulating CD4+ T cells of young melanoma patients show clear signs of an ongoing immune response, whereas these signs are lacking in CD4+ T cells of old melanoma patients." (PMID 29546435, 2018). "Another study in BRAF V600E mouse melanoma transplants and in de novo melanomas demonstrated that BRAF inhibitor downregulated tumor expression of chemokine (C-C motif) ligand 2 (CCL2), and resulted in a robust increase in CD8+ T/FoxP3+CD4+ T cell ratio and natural killer (NK) cells." (PMID 29156850, 2017). "We have previously shown that insertion of CD8 epitopes TRP2 (aa180-188) and CD4 epitopes from gp100 (aa44-59 and 174-190) into human IgG1 antibody DNA vaccine (SCIB1) induces high frequency and avidity CD8 and CD4 T cell responses in mice and melanoma patients." (PMID 27825115, 2016). "Induction of the antitumor response in primary tumors did not require CD4+ T cell populations in B16 melanoma or disseminated pancreatic tumors, although in treated mice that survived the primary cancer, CD4+ T cells were shown to play an important role in enforcing immunity to pancreatic cancer." (PMID 27447180, 2016). "To investigate whether OVA-specific CD4+ and CD8+ T cells primed with desialylated sDCs would have a higher ability to induce tumor cell cytotoxicity, we co-cultured the primed T cells with the OVA-expressing melanoma cell line B16-OVA." (PMID 27203391, 2016). "Conversely, the depletion of CD4+ T cells alone or the activation of the innate immune system with LPS alone induces weak antitumor CD8+ T cell immune responses in non-irradiated animals with melanoma." (PMID 26885368, 2016). "Immunization with antigen-pulsed mature DCs, which aims to elicit antitumor T cell responses, may in fact also lead to significant antitumor immunity in an NK cell-dependent manner, reflecting interplay between DC, NK and CD4+ and/or CD8+ T-cells as reported in melanoma and other tumor models." (PMID 26405163, 2015). "We observed that TAA-specific CD4+ T cells were readily detectable in the peripheral blood of melanoma patients, regardless of whether these individuals had AD or if they were NED as a consequence of therapeutic intervention." (PMID 25325015, 2014).
melanoma (continued). "Since patients with melanoma containing a higher number of T lymphocytes show longer overall survival than those bearing tumors without T lymphocytes infiltrations, we analyzed the subpopulation of T lymphocytes including the number of CD8+ and CD4+ T cells in CD45+ cells." (PMID 25594054, 2014). "Our data would predict that a similar differential imbalance between pro (Bax)-/anti (Bcl-2, Bcl-xL, Mcl-1, Xiap)-apoptotic proteins is likely to occur within the subset of TAA-specific (but not bulk or viral-specific) CD4+ T cells in the peripheral blood of melanoma or RCC patients with AD." (PMID 25325015, 2014). "USP18 expression in B16 melanoma tumor cells regulated IFN-γ-mediated immunoediting, including upregulating MHC class-I expression, reducing tumor cell-mediated inhibition of T cell proliferation and activation, and suppressing PD-1 expression in CD4+ and CD8+ T cells in tumor-bearing mice." (PMID 24884733, 2014). "However, downregulation of Smad4 by neither ALK5 inhibition nor T-cell-specific gene targeting affected any CD4+ T-cell subsets in melanoma-bearing mice." (PMID 24127404, 2013). "Purified CD4+ T cells were stimulated with beads coated with anti-CD3 and anti-CD28 antibodies and co-transduced with a lentivirus expressing codon-optimized CD8α and individual CD8β isoforms and a second lentivirus expressing TCRαβ from a CD8 dependent TCR recognizing the melanoma antigen NY-ESO-1." (PMID 23533620, 2013). "In our present study, IFN-γ is found to directly promote expression of cytotoxic molecules in CD4+ T cells, which is consistent with an early report that activation of IFN signaling was required for expression of perforin and granzyme in CD8+ T cells and NK cells in melanoma patients." (PMID 23145026, 2012). "We previously reported the absence of recognition of HLA-matched melanoma cell lines by two CD4 T cell clones specific for the C-term region of the antigen, that seemed consistent with the fact that MELOE-1 has no signal peptide, nor endosomal targeting sequence." (PMID 23284752, 2012). "Lymphopenia-induced homeostatic T cell proliferation in the context of a progressive melanoma, and the absence of CD4+CD25+ regulatory T cells (Treg), is sufficient to break tolerance and induce vitiligo, likely due to the removal of both suppression and homeostatic cytokine sinks." (PMID 21911918, 2011). "Interestingly, SSX2 CD4+ T cells failed to recognize IFNγ-treated melanoma cells expressing SSX2 and class II MHC molecules (HLA-DP); however, they were stimulated by antigen-loaded dendritic cells." (PMID 20981248, 2010). "Importantly, we confirmed TRP-2149–163 to be naturally processed and presented also in the human system, as already shown for TRP-260–74, and we could detect epitope-specific CD4+ T cells among PBMC of both, melanoma patients and healthy individuals." (PMID 21152437, 2010). "These professional and nonprofessional APCs as well as tumors such as melanoma could then be able to present this repertoire of epitopes to CD4+ T cells, further priming an immune response and leading to the ablation of tumor cells." (PMID 20016802, 2009). "We found that transient depletion of CD4+ and CD8+ T cells in melanoma patients via targeting of IL-2 receptor-expressing cells resulted in T cell repopulation in the peripheral blood and the de novo appearance of CD8+ T cells with specificity for melanoma antigens (in 4/7 HLA-A2*0201 patients)." (PMID 18334033, 2008). "Of major interest, we determined that freshly-isolated PBMC frequencies of Th1-type CD4+ T recognizing these peptides are frequently elevated in HLA-DR4+ melanoma patients (but not normal donors) that are currently disease-free as a result of therapeutic intervention." (PMID 11742496, 2001).
melanoma (continued). "Indirect evidence for their positive effect comes from the observation that melanoma tumors expressing HLA-II proteins, HLA-II(+), have better prognosis than HLA-II(─) tumors, but this differential effect could also be due to the facilitation of CD8+ T cells by activated CD4+ T cells." (PMID 41002395, 2025). "In melanoma tumor model, the in‐situ hydrogel could greatly promote the DCs maturation, induce sufficient T lymphocyte in LNs, eventually increase the proportion of CD8+ and CD4+ T cells in tumors, and effectively control the growth of tumor and lung metastasis." (PMID 38962939, 2024). "Despite the observed resistance of certain cancer cell types in vitro (e.g. melanoma), IT injection of unconjugated Accum® could delay pre-established EL4 T-cell lymphoma growth when combined with ICIs; a therapeutic effect that seems to depend on dendritic cells as well as CD4 and CD8 lymphocytes." (PMID 38831284, 2024). "Moreover, CY12-RP2 could inhibit melanoma lung metastasis, and abrogated the immunosuppressive effects of PDPN by increasing the proportion of CD3 + CD4 + T cells, CD3 + CD8 + T cells, CD49b + Granzyme B + NK cells, and CD11b + CD86 + M1-like macrophages and the levels of IL-1β, TNF-α, and IFN-γ." (PMID 38167452, 2024). "To determine whether immune scMEP marker expression correlated with ex vivo melanoma antigen-specific T-cell responses, we observed that CD11c and PD-L1 were significantly elevated in mDCs from patients with positive CD8 and combined CD8 + CD4 T cells responses." (PMID 37938561, 2023). "In a B16 melanoma model, LOFU treatment, compared to no treatment, led to a decreased transcriptional expression of multiple anergy-associated genes, including three E3 ubiquitin ligase genes named GRAIL, Cbl-b, and Itch within CD4+ T-cells isolated from tumor-draining lymph nodes." (PMID 37626741, 2023). "We did not detect correlations with CD8+ and CD4+ T-cell responses with circulating DC metabolism, however we observed an increased expression of the checkpoint receptor ILT3 on selected monocyte and conventional DC subtypes in melanoma patients, which significantly associated with decreased OS." (PMID 37938561, 2023). "Recent researches reported that CD4 + T lymphocytes and CD8 + T lymphocytes infiltrating in tumor could improve the efficacy of tumor-targeted vaccine or adoptive immune cell therapy, which had been proved effective in patients with melanoma, head and neck cancer, breast cancer, and lung cancer." (PMID 34281486, 2021). "CD4+ cells after uptake OVA-pulsed DEXs could stimulate efficient antigen-specific CTL responses and long-term T CD8+ cell memory in immunized C57BL/6 mice against OVA-transfected melanoma cells expressing OVA challenge after three months of complete immunization." (PMID 34335627, 2021). "The study of matched pre/on-treatment biopsies of melanoma patients having received an anti-PD-1 revealed a decrease in frequency of effector memory CD4 + T cells post-treatment, whilst an on-treatment increase in intratumoral CD4 + effector T cells was found to be a negative correlate of response." (PMID 33602280, 2021). "An earlier study showed that a low percentage of Ki67+EOMES+CD4+ T cells at baseline (but not under treatment) was associated with the occurrence of irAE in a study using adjuvant treatment of stage III and stage IV melanoma patients with anti-CTLA antibody ipilimumab." (PMID 34360781, 2021). "In melanoma, these signatures were predominantly found in the lymphoid compartment and mainly involved different baseline expression patterns of PD-1 and/or PD-L1: the expression of PD-L1/PD-1 in non-proliferating (Ki67−) CD8+ and CD4+ T cells was associated with worse clinical outcome." (PMID 34071888, 2021).
melanoma (continued). "Furthermore, in B16-F10 melanoma-bearing mice, PCC0208025 presented the antitumor effects, enhanced IFN-γ levels in plasma, increased the frequency of CD3+CD8+ T and CD8+IFN-γ+ T and the ratios of CD8+/Treg, and deceased the CD4+CD25+CD127low/− (Treg) number in tumor." (PMID 32214351, 2020). "Similarly, in a murine model of melanoma, T-cell cytokines IFN-γ and TNF-α synergized with vemurafenib, a BRAF oncogene inhibitor, to induce cell-cycle arrest of tumor cells in vitro, underscoring the importance of CD4+ T cell mediated immunity against cancer cells." (PMID 27766079, 2016). "Thus while CD4 T cell help could still contribute to the generation of an optimal CD8 T cell response to melanoma, the present studies establish that help is not an absolute requirement for functional, long-lived memory." (PMID 22046294, 2011). "Therefore CD4 T cell help was not required for protective memory to melanoma." (PMID 22046294, 2011). "However, studies by two independent groups demonstrated that murine CD4+ T cells specific for TRP-1, upon adoptive transfer into a lymphopenic host, differentiated into cytolytic, IFN-γ secreting effectors that directly killed MHC class II-positive B16 melanoma cells." (PMID 21152437, 2010). "Again, as was found for the SSX2 class II peptides, CD4+ T cells could not recognize melanoma cells directly but were activated by APCs loaded with SSX4 antigen, which suggested that this peptide may not be presented through the endogenous pathway in tumor cells." (PMID 20981248, 2010). "This cell subset was positive for the CD3 marker but negative for CD4 and CD8, and it was at higher frequencies in BrMs (10% in melanoma BrM)." (PMID 39751910, 2025). "In these samples, all NK cells were excluded from the tumor area and co-localized with CD4+ T cells, CD8+ T cells, DCs, and B cells either outside of the tumor parenchyma and/or surrounding blood vessels in regions lacking melanoma cells." (PMID 40530504, 2025). "This analysis showed significant CD8+ and CD4+ T-cell infiltration after subasumstat administration in samples from CPI-naïve (cervical cancer) and CPI-exposed (melanoma and NSCLC) patients; no significant changes in regulatory T cells were observed." (PMID 41134690, 2025). "We found for the first time that melanoma patients who did not respond to immunotherapy exerted increased cellular senescence in their CD8+ T-cells, CD4+ T-cells, B-cells (CD19+/CD20+) and NK cells compared to responders." (PMID 41372921, 2025). "The TMAs for the lung, glioma, and the breast cancers show a lower occurrence frequency of T cell (CD4+/CD8+, not Tregs) fencing with < 70 % patients as compared to melanoma, HNC and CRC." (PMID 41446806, 2025). "Here, pharmacological SPOP inhibition stabilizes and activates tumor STING, driving infiltration of CD4+, but not CD8+, T cells, thereby improving anti–PD-1 efficacy in B16 melanoma." (PMID 41148213, 2025). "Melanoma patients who did not respond to immunotherapy exhibited increased cellular senescence in the CD8 + T-cell, CD4 + T-cell, B-cell (CD19 + /CD20 +) and NK cell compartments compared to responders." (PMID 41372921, 2025). "Regarding mucosal melanoma patients, ratios of CD8+/CD4+ lower than 2 predicted a lack of response to treatment, while ratios higher than 2.7 had an 81.3% response rate." (PMID 39199634, 2024). "Residual melanoma hence may not be successfully eliminated by any local de novo forming immune response or by any pre-existing melanoma-specific immune surveillance through CD4+ and CD8+ memory T and B cells generated during an encounter with the primary tumor." (PMID 38672543, 2024). "Melanomas negative for PD-L1 show a significant degree of staining (2+) by CD4 and CD8 infiltrating lymphocytes (CD8+TILs: 58.53%; MTCs: 75.76%, CD4+TILs: 70.83%; MTCs: 87.88%, p < 0.05)." (PMID 36836455, 2023).